MBL2 (mannose binding lectin 2)
Diseases named in the same sentence as MBL2 in open-access papers (continued):
Sharing a sentence is not in itself a finding about the gene and the disease.
hepatocellular carcinoma (10 papers, 2015 to 2026). A malignant tumor that arises from hepatocytes. "The MBL2 (rs7096206) is associated with risk of hepatocellular carcinoma and febrile neutropenia however the genotype have not been studied in relation to NHL." (PMID 26448050, 2015). "The studies regarding the association between MBL2 polymorphisms and cancer risk have been seldom reported, as for hepatocellular carcinoma, only a study conducted in Italian population investigated the relationship between polymorphisms in the exon 1 of MBL2 and HCC risk." (PMID 27557564, 2016). "MBL2 gene polymorphisms are associated with the risk and prognosis of various tumors, including hepatocellular carcinoma (HCC)." (PMID 37835594, 2023). "Our objective was to investigate the influence of MBL2 on the proliferation and metastasis of hepatocellular carcinoma using integrated multi-omics analysis and experimental validation, with a specific emphasis on MBL2-related microRNAs." (PMID 37835594, 2023). "We verified the promoting effect of miR-34c-3p in hepatoma cells and predicted its target on MBL2 through bioinformatics, suggesting miR-34c-3p targeting MBL2 promotes HCC development." (PMID 37835594, 2023). "In addition, we combined in vivo and cellular experiments to confirm that low MBL2 expression promotes the basic oncogenic functions of hepatoma cells." (PMID 37835594, 2023). "This study focuses on understanding the role of mannose-binding lectin 2 (MBL2) in hepatocellular carcinoma (HCC) and its potential as a target for therapy." (PMID 37835594, 2023).
pancreatic cancer (10 papers, 2010 to 2026). "Of these, Tagln2 has previously been linked to angiogenesis, proliferation, migration, and epithelial–mesenchymal transition in GC, while Mbl2 gene variants have been linked to risk of stomach cancer and increased serum levels linked to pancreatic cancer." (PMID 38542101, 2024). "Serum levels of MBL2 have been reported to be significantly higher in pancreatic cancer patients suggesting possible involvement in cancer progression." (PMID 26414287, 2015). "Mannose-binding lectin 2 and myosin light chain kinase 2, a serine/threonine kinase, were identified as potential biomarkers for the pancreatic cancer diagnosis and further validated by western blot in an independent set of sera from pancreatic cancer patients and normal controls." (PMID 23401773, 2013). "Similarly, the mannose binding lectin 2 (MBL2), a mediator of inflammation which results iperexpressed in pancreatic cancer sera, is involved in cancer processes." (PMID 23401773, 2013). "Up-regulation of mannose-binding lectin 2 and myosin light chain kinase 2, which have not previously been implicated in pancreatic cancer, were observed." (PMID 20587030, 2010). "We further confirmed the expression levels of two up-regulated proteins (MBL2 and MLCK2) in the sera from pancreatic cancer patients using western blot analysis." (PMID 20587030, 2010). "MBL2, which was found in this study to be increased in pancreatic cancer serum, has not been identified previously as a marker of pancreatic cancer." (PMID 20587030, 2010). "In an independent series of serum samples from 16 patients with pancreatic cancer and 16 non-cancer-bearing controls, increased levels of mannose-binding lectin 2 and myosin light chain kinase 2 were confirmed by western blot." (PMID 20587030, 2010). "MBL2 and MLCK2 were identified for the first time as serum biomarkers in pancreatic cancer." (PMID 20587030, 2010). "Further validation studies in an independent set of serum samples from 16 pancreatic cancer patients and 16 non-cancer-bearing controls demonstrated increased levels of MBL2 and MLCK2." (PMID 20587030, 2010). "In our study, we showed for the first time that the serum levels of MBL2 were significantly higher in pancreatic cancer patients than in the non-cancer-bearing controls, suggesting that MBL2 might represent a new serum marker for pancreatic cancer." (PMID 20587030, 2010).
rheumatoid arthritis (10 papers, 2008 to 2023). A chronic, systemic autoimmune disorder characterized by inflammation in the synovial membranes and articular surfaces. "In a Brazilian cohort, we aim to associate the functional role of circulating MBL serum levels and MBL2 variants in clinically classified patients (n = 196) with rheumatoid arthritis including their relatives (n = 200) and ethnicity matched healthy controls (n = 200)." (PMID 24751721, 2014).
diabetic nephropathy (9 papers, 2010 to 2022). "Taken together, circulating MBL levels are associated with diabetic nephropathy and are dependent on glycaemic control, possibly in an MBL2-genotype-dependent manner." (PMID 26768002, 2016). "The first aim of the present study was to investigate the association of MBL2 gene polymorphisms with type 2 diabetes and diabetic nephropathy in a Chinese Han population." (PMID 24376633, 2013). "Among these proteins, increased levels of mannose-binding protein C (Mbl2), cystatin C (Cst3), and proto-oncogene vav (Vav1) might increase the risk of diabetic nephropathy." (PMID 36335368, 2022). "Analyses of genotypes and allele frequency distributions among patients with normal UAE, microalbuminuria, and macroalbuminuria showed that there was no obvious evidence of association between the MBL2 gene and diabetic nephropathy." (PMID 24376633, 2013). "We assessed MBL levels and corresponding MBL2 genotype, together with vascular endothelial growth factor (VEGF) levels as a marker of vascular damage, in type 1 diabetes patients with diabetic nephropathy before and after simultaneous pancreas–kidney (SPK) transplantation." (PMID 26768002, 2016).
influenza (9 papers, 2011 to 2021). An acute viral infection of the respiratory tract, occurring in isolated cases, in epidemics, or in pandemics; it is caused by serologically different strains of viruses (influenzaviruses) designated A, B, and C, has a 3-day incubation period, and usually lasts for 3 to 10 days. "We did identify one child carrying an extremely rare, highly deleterious mutation in MBL2, further adding to the literature that rare variants play some role in severe influenza infection susceptibility." (PMID 31139182, 2019). "In humans, polymorphism in the MBL2 gene has been previously shown to affect immune reactions to influenza vaccine." (PMID 24558451, 2014). "An obvious next step is examination of all functional variants of the MBL2 gene in conjunction with gene expression and functional assays in a larger group of severely ill influenza case-patients with sufficiently detailed clinical data to define important phenotypes (e.g., MRSA co-infection)." (PMID 22172537, 2011). "Among children and young adults who died of influenza, low-producing MBL2 genotypes may have increased risk for MRSA co-infection." (PMID 22172537, 2011). "Therefore, we evaluated associations between MBL2 variants and overall influenza susceptibility, severity, and bacterial co-infection in a multicenter prospective cohort of critically ill children and adolescents in the Pediatric Intensive Care Influenza (PICFLU) Study." (PMID 31139182, 2019). "Characteristics and MBL2 genotype and MBL level (when available) of children with fatal influenza MRSA co-infection in the PICFLU cohort." (PMID 31139182, 2019). "They reported that influenza cases leading to death with concomitant methicillin-resistant Staphylococcus aureus (MRSA) infection had a higher incidence of low-production MBL2 genotype compared to the cases of death without MRSA co-infection." (PMID 33766078, 2021).
systemic lupus erythematosus (9 papers, 2006 to 2023). An autoimmune multi-organ disease typically associated with vasculopathy and autoantibody production. "In contrast, homozygosity for MBL2 alleles that predicted low MBL levels was higher in Danish patients with systemic lupus erythematosus than in control subjects, and was associated with significantly greater infection risk." (PMID 31117958, 2019).
coronary artery disease (8 papers, 2014 to 2022). "Previous studies within the SHS cohort identified an association between MBL2 genotypes and coronary artery disease." (PMID 30629683, 2019). "MBL2 dysregulation is associated with coronary heart disease (CHD) and increased susceptibility to microbial infection." (PMID 30629683, 2019). "However, in a large prospective study of apparently healthy individuals, high‐serum MBL‐2 levels in men were associated with a higher risk of developing coronary heart disease in future." (PMID 34492130, 2021). "A high prevalence of coronary artery disease (CAD) is associated with high MBL‐2 levels." (PMID 34492130, 2021). "Studies have also shown that individuals with coronary artery disease had higher serum levels of MBL‐2, TNC, and MDA but lower serum levels of TAC." (PMID 34492130, 2021). "The results of our study showed that the serum level of MBL‐2 was significantly increased in patients with coronary artery disease compared to the control group." (PMID 34492130, 2021). "This study mainly aims to investigate the serum levels of some biochemical markers such as MBL‐2, TNC, TAC, and MDA in patients with CAD to determine the relationship and dependence of these parameters on the severity of coronary artery disease." (PMID 34492130, 2021). "Patients with and without coronary artery disease (CAD) who received an agent for atherosclerosis and periodontitis (PD) had lower serum MBL‐2 levels." (PMID 34492130, 2021).
diabetes (8 papers, 2013 to 2025). "A protective role for high MBL levels were reported in myocardial infarction, particularly in diabetes, and MBL2 variants related to functional MBL deficiency were shown to increase by twofold the risk of myocardial infarction in healthy individuals." (PMID 25654073, 2014). "Additionally, the presence of the Y or H variants in the MBL2 promoter strongly correlated with a prior diagnoses of diabetes (rs = -0.106.111; p = <0.01 for both)." (PMID 30629683, 2019). "The possible explanation of the contradictory results between the MBL2 gene and diabetes may be that the variants of the MBL2 gene have significant racial differences and only a few polymorphisms have been studied in relatively small samples." (PMID 24376633, 2013). "Muller’s study showed that the association between genes and diabetes was restricted to the region in the MBL2 gene, which means that evidence of association with type 2 diabetes is more likely to be derived from the MBL2 gene rather than from other genes." (PMID 24376633, 2013). "Replication analysis conducted on 385 IA cases from The Environment Determinants of Diabetes in the Young (TEDDY) study confirmed 68 significant (FDR < 0.05) pQTLs in total for C8A, C8B, CFB, C4A, and MBL2." (PMID 39989961, 2025).
pulmonary tuberculosis (8 papers, 2011 to 2020). A bacterial infection that affects the lungs and is caused by Mycobacterium tuberculosis. "In a cohort from the northeastern region of Brazil, MBL2 promoter polymorphisms were linked with increased susceptibility to pulmonary TB." (PMID 32582566, 2020). "Many epidemiologic studies, including meta-analyses, suggest that there are relationships between MBL2 gene variations and pulmonary TB (PTB) risk." (PMID 32746927, 2020). "This is the first study to investigate the association between MBL2 polymorphisms with pulmonary TB susceptibility in northern Han Chinese." (PMID 27812036, 2016). "We analysed the six promoter and structural mannose-binding lectin 2 gene variants in 107 patients with pulmonary tuberculosis and 441 healthy controls." (PMID 23304495, 2012). "We explored whether MBL2 polymorphisms or MBL levels are associated with the development of pulmonary TB (PTB) in China, a country with high TB prevalence." (PMID 28298186, 2017). "In this study four functional single-nucleotide polymorphisms (SNPs, H/L, X/Y, P/Q and A/B) across the MBL2 gene were genotyped by direct DNA sequencing of PCR products in a case-control population of Chinese Han origin, consisting of 1,020 patients with pulmonary TB and 1,020 controls." (PMID 27812036, 2016). "We have studied the influence of MBL2 variants on susceptibility and resistance to TB by comparing HIV-negative patients with smear- and/or culture-positive pulmonary TB to unaffected and unrelated control individuals in Ghana, West Africa." (PMID 21695215, 2011).
atherosclerosis (7 papers, 2009 to 2023). A disease characterized by the build-up of fatty material and calcium deposition in the arterial wall resulting in partial or complete occlusion of the arterial lumen. "This suggests that MBL‐2 levels reflect or contribute to a pathophysiological process associated with the development of atherosclerosis." (PMID 34492130, 2021). "Another reason was our previous finding that MBL2 was more strongly associated with severe atherosclerosis in the youngest patients going through coronary surgery." (PMID 22848725, 2012). "There is some evidence for the role of Mannose binding lectin‐2 (MBL‐2) in the development of atherosclerosis." (PMID 34492130, 2021). "Prospective epidemiologic studies, including a nested, case-control study from the present population, have demonstrated the ability of MBL2 genotypes to predict complications of atherosclerosis." (PMID 19161617, 2009). "Future preclinical studies should analyse whether modified EVs loaded with a low expression of APOB and FL and an overexpression of LRP1 and MBL2 could reduce atherosclerosis formation." (PMID 33374290, 2020). "In humans, variant MBL2 alleles may be correlated with increased carotid plaque area and MBL deficient individuals may also have higher postprandial lipid values, which in turn may contribute to the development of atherosclerosis." (PMID 22848725, 2012). "We found that APOB, FN, MBL2, and miR-340 could be involved in atherosclerosis formation in IS but not in MI, suggesting different processes underlying ischaemia, depending on the affected organ." (PMID 33374290, 2020).
colon cancer (7 papers, 2013 to 2021). "Furthermore, a single study has indicated that rs2099902, rs10082466 variants of 3′-UTR and functional secretor haplotypes in MBL2 are associated with increased colon cancer risk in African Americans." (PMID 27390651, 2016). "The reduction on MBL2 level in cancer patients has been confirmed among 261 colon cancer cases and 537 controls in United States12, and the ethnicity also has impact on the MBL2 level." (PMID 27557564, 2016). "Several reports demonstrated the significance of MBL2 gene SNPs in gastric, hepatic or colon cancers, glioma and acute lymphoblastic leukaemia." (PMID 25038892, 2014).
Immunodeficiency (7 papers, 2014 to 2020). Failure of the immune system to protect the body adequately from infection, due to the absence or insufficiency of some component process or substance. "MBL2 is a member of the lectin family, which has been associated with immune dysfunction and is commonly expressed in immune disorder-related diseases." (PMID 33603663, 2020). "MBL is an important acute-phase serum protein involved in the innate immune response that can trigger complement activation, and an association between allele ∗B in the exon 1 of the MBL2 gene has been reported with the occurrence of immunodeficiency and chronic infectious diseases." (PMID 29379480, 2017).
Stroke (7 papers, 2010 to 2020). Sudden impairment of blood flow to a part of the brain due to occlusion or rupture of an artery to the brain. "In order to investigate the clinical relevance of these experimental observations, a study of MBL2 and MASP-2 gene polymorphism rendering the lectin pathway dysfunctional was performed in 135 stroke patients." (PMID 20140243, 2010).
type 1 diabetes (7 papers, 2013 to 2023). "Most studies focused on the association of the MBL2 gene with type 1 diabetes and the conclusions were controversial." (PMID 24376633, 2013).
bacteremia (6 papers, 2011 to 2019). "To define independent associations between persistent bacteremia and the significant clinical factors and MBL2 genotype groups, we constructed a multivariate logistic regression model using bootstrapping." (PMID 24595015, 2014). "The aim of this study was to investigate whether low MBL-producing MBL2 genotypes or low MBL levels confer an increased risk for persistent S. aureus bacteremia." (PMID 24595015, 2014). "Also, the MBL2 variant rs930507 is overrepresented in bacteremia cases among AA (allelic OR 1.82, p = 0.046) with a similar effect in EA (allelic OR 1.19) but with p>0.3." (PMID 21858107, 2011). "Therefore, MBL2 genotypes could be of clinical interest as a molecular marker to identify patients with S. aureus bacteremia who are at risk for persistent bacteremia." (PMID 24595015, 2014). "Comparison of MBL2 genotype groups in patients with Staphylococcus aureus bacteremia or patients with persistent bacteremia versus healthy people." (PMID 24595015, 2014). "In agreement with the difference in the proportions of MBL2 genotype groups between patients with persistent and resolving bacteremia, serum MBL concentrations were significantly lower in patients with persistent bacteremia (P = 0.012)." (PMID 24595015, 2014). "Population-based birth cohort studies showed no increased risk of invasive (bacteremia or meningitis) meningococcal or pneumococcal disease in Danish children carrying low-producing MBL2 variants." (PMID 31139182, 2019).
co-infection (6 papers, 2011 to 2021). "In one report, MBL2 alleles and genotypes were assessed in a Western European population for association with co-infection." (PMID 32582566, 2020). "Low-producing MBL2 genotypes may have increased risk for MRSA co-infection." (PMID 22172537, 2011). "Fatal cases with low-producing MBL2 genotypes had a 7-fold increased risk for invasive methicillin-resistant Staphylococcus aureus (MRSA) co-infection compared with fatal cases with high- and intermediate-producing MBL2 genotypes (odds ratio 7.1, 95% confidence interval 1.6–32.1)." (PMID 22172537, 2011). "Distribution of participants between MBL2 promoter region haplotypes according to HIV and S. haematobium co-infection status." (PMID 25830474, 2015).
cystic fibrosis (6 papers, 2013 to 2024). Autosomal recessive disorder caused by pathogenic variants in the CFTR gene (cystic fibrosis transmembrane conductance regulator), which encodes a chloride and bicarbonate channel expressed in epithelial cells, and follow the diagnosis criteria. "In other diseases, such as cystic fibrosis, it was reported that MBL2 deficiency was associated to infection with Pseudomonas aeruginosa and Burkholderia cepacia." (PMID 26684757, 2015). "MBL2 mutations and the consequent Mannose Binding Lectin deficit have been previously associated with cystic fibrosis and recovery from infections." (PMID 23844243, 2013). "Moreover, Yokoyama E and colleagues proved that the MBL2 rs11003125 GG or GC genotype was significantly associated with patients with cystic fibrosis as a risk factor." (PMID 38167099, 2024). "This is consistent with previous studies which found that MBL2 deficiency was associated with worse outcomes in patients with cystic fibrosis." (PMID 36636720, 2022). "In cystic fibrosis, MBL2 levels correlated with reduced FEV1 % predicted." (PMID 26684757, 2015).
hepatitis B (6 papers, 2013 to 2026). "A meta-analysis was performed to examine the association between mbl2 polymorphisms and chronicity or progression of hepatitis B infection." (PMID 24116040, 2013). "Moreover, it was reported that the mbl2 polymorphisms may be an important factor in determining the prognosis in patients with hepatitis B virus infection." (PMID 24116040, 2013).
IgA nephropathy (6 papers, 2018 to 2026). "Transcriptomic-wide MR identified candidate genes across GN subtypes: RECQL, BRSK2, and MGP in acute GN; AFM, CFHR5, and EPHB2 in chronic GN; IL6R, MBL2, and PRSS3 in IgA nephropathy; and TIMP4, HCK, and PEAR1 in membranous nephropathy." (PMID 41990104, 2026).